TFB1M (transcription factor B1, mitochondrial)
Description:
Mitochondrial methyltransferase which uses S-adenosyl methionine to dimethylate two highly conserved adjacent adenosine residues (A1583 and A1584) within the loop of helix 45 at the 3-prime end of 12S rRNA, thereby regulating the assembly or stability of the small subunit of the mitochondrial ribosome. Also required for basal transcription of mitochondrial DNA, probably via its interaction with POLRMT and TFAM. Stimulates transcription independently of the methyltransferase activity.
Synonyms: mtTFB1; CGI-75; mtTFB; CGI75
Tractability: Small molecule: a structure with a bound ligand is known. PROTAC: its protein half-life has been measured.
Gene: Protein-coding gene on chromosome 6 (155,256,134 to 155,314,493, reverse strand). Ensembl gene ENSG00000029639.
Subcellular location: Mitochondrion
Pathways (Reactome):
Metabolism of RNA: rRNA modification in the mitochondrion
Organelle biogenesis and maintenance: Transcriptional activation of mitochondrial biogenesis
Gene Ontology:
Molecular function: protein binding; RNA binding; rRNA (adenine-N6,N6-)-dimethyltransferase activity; S-adenosyl-L-methionine binding; mitochondrial transcription factor activity
Biological process: mitochondrial small ribosomal subunit assembly; rRNA methylation; rRNA modification; transcription initiation at mitochondrial promoter; rRNA processing
Cellular component: mitochondrial nucleoid; mitochondrion; mitochondrial matrix
Genetic constraint (gnomAD): Loss-of-function variants: 22 observed, 28.59 expected, observed/expected ratio (o/e) 0.77, 90% interval 0.55 to 1.1. The upper end of that interval is the gene's LOEUF score, 1.1, which puts it in group 4 of 6, group 1 being the genes least tolerant of losing a copy. Missense variants: 358 observed, 398.45 expected, observed/expected ratio (o/e) 0.9, 90% interval 0.82 to 0.98. Synonymous variants: 152 observed, 146.24 expected, observed/expected ratio (o/e) 1.04, 90% interval 0.91 to 1.19.
Homologues: Orthologues: chimpanzee TFB1M (99% identical), macaque TFB1M (94% identical), dog TFB1M (88% identical), rabbit TFB1M (87% identical), guinea pig TFB1M (86% identical), rat Tfb1m (85% identical), mouse Tfb1m (84% identical), pig TFB1M (84% identical), tropical clawed frog tfb1m (74% identical), zebrafish tfb1m (57% identical), Drosophila melanogaster mtTFB1 (47% identical), Caenorhabditis elegans tfbm-1 (43% identical). Paralogues in human: DIMT1 (22% identical), TFB2M (17% identical).
Diseases named in the same sentence as TFB1M in open-access papers:
TFB1M is named in the same sentence as 20 diseases in open-access papers, as found by Europe PMC text mining. Sharing a sentence is not in itself a finding about the gene and the disease. The quoted sentences say what the papers report.
type 2 diabetes (6 papers, 2014 to 2024). "Variations or low expression of TFB1M have been associated with decreased insulin secretion in type 2 diabetes patients." (PMID 38809515, 2024). "A separate study identified a common variant of human TFB1M (rs950994) associated with impaired insulin response, elevated glucose levels, and increased risk of type 2 diabetes." (PMID 33917098, 2021). "Gene variants in other mitochondrial transcription factors, namely TFB1M, have been found to correlate with reduced insulin secretion, elevated postprandial glucose levels and increased risk of developing type 2 diabetes." (PMID 25532126, 2014). "Interestingly, another study found a common variant of TFB1M to be associated with reduced insulin secretion and increased risk of type 2 diabetes in Tfb1m-deficient mice." (PMID 32765591, 2020). "Similar observations were documented for a mouse model with beta cell-specific knockout of Tfb1m that resulted in lower insulin secretion, mitochondrial dysfunction, and eventual development of type 2 diabetes." (PMID 33917098, 2021).
deafness (5 papers, 2010 to 2023). An inherited or acquired condition characterized by the complete loss of the ability to hear from one or both ears. "TWAS implicated TFB1M, a modulator gene for inherited deafness and associated with intelligence in GWAS." (PMID 36760791, 2022). "TFB1M was initially linked to aminoglycoside antibiotic-induced deafness because studies using TFB1M transgenic mice showed activation of pro-apoptotic factor E2F1 caused by TFB1M-hypermethylation of mt-12S rRNA." (PMID 32765591, 2020). "Defects in the 30 shared genes are related to several pathologies, such as vision abnormalities (TMEM135), cancer (CDH6, FZD10, TIAM2), neuropsychiatric disorders (Tenm4, Pde4dip, Grid2), deafness (TFB1M), neutrophil disorders (VPS45) and others." (PMID 36902345, 2023). "Using this method, the DFNM1 locus, a modifier of DFNB26-linked deafness was identified and the deafness phenotype associated with the 1555A>G mutation in MTRNR1 was shown to be modified by three different genes: MTO1, TFB1M and GTPBP3." (PMID 21119891, 2010).
hearing loss (4 papers, 2015 to 2022). "TFB1M—TFB1M was initially thought to be a modifier gene for hearing loss associated with the m.A1555G mutation; however, this was later questioned as patients with the m.A1555G mutation had similar 12S rRNA methylation levels to controls." (PMID 33917098, 2021). "TFB1M is located on chromosome 6 and encodes for one of several proteins that regulate mtDNA transcription and replication, and is associated with mitochondrial non-syndromic sensorineural deafness, and drug-induced hearing loss." (PMID 36760791, 2022).
glioblastoma (2 papers, 2018 to 2024). The most malignant astrocytic tumor (WHO grade IV). "In the present study, we showed that TFAM and other mitochondrial transcription factors (TFB1M and TFB2M) may be targets of melatonin in glioblastoma cells." (PMID 29747444, 2018). "In summary, our results suggest that increased generation of melatonin-induced intracellular ROS in U87MG glioblastoma cells may be an effect of melatonin on the expression of TFAM and other mitochondrial transcription factors (TFB1M and TFB2M), leading to mitochondrial disruption." (PMID 29747444, 2018).
glioma (2 papers, 2021 to 2024). A benign or malignant brain and spinal cord tumor that arises from glial cells (astrocytes, oligodendrocytes, ependymal cells). "Our findings revealed that MRM2, NSUN4, TFB1M, and TRMT2B were correlated significantly with most immunomodulators in glioma, whereas MRM1 and RPUSD4 were correlated negatively." (PMID 34566979, 2021).
Cirrhosis (1 paper, 2023). A chronic disorder of the liver in which liver tissue becomes scarred and is partially replaced by regenerative nodules and fibrotic tissue resulting in loss of liver function. "Analyses of expression data in GSE14323 showed increased expression of ZNF281 in HCC compared with normal and cirrhosis liver tissues but decreased expression of PGC-1α, TFAM, TFB1M, and TFB2M." (PMID 37880213, 2023).
diabetes (1 paper, 2024). "We used machine learning to identify six key genes closely associated with vascular aging in diabetes: TFB1M, FOXRED2, LY75, DALRD3, PI4K2B, and NDOR1." (PMID 38809515, 2024). "Using bioinformatics and machine learning techniques, we identified six key genes that are closely associated with vascular aging in diabetes: TFB1M, FOXRED2, LY75, DALRD3, PI4K2B, and NDOR1." (PMID 38809515, 2024). "Moreover, low expression of TFB1M has also been associated with cellular senescence and organelle damage in diabetes." (PMID 38809515, 2024). "As a mitochondrial transcription factor, TFB1M can regulate mitochondrial DNA transcription and repair, thereby protecting mitochondrial function and improving energy metabolism and insulin secretion in diabetes." (PMID 38809515, 2024). "However, no studies have yet shown whether low expression of TFB1M in diabetes can cause vascular aging." (PMID 38809515, 2024). "The expression of TFB1M, FOXRED2, DALRD3, PI4K2B, and NDOR1 was negatively correlated with vascular aging in diabetes, while LY75 expression was positively correlated." (PMID 38809515, 2024).
diabetic nephropathies (1 paper, 2024). "In UK-ROI, AGXT2-rs71615838 and SURF1-rs183853102 were associated with diabetic nephropathies, and TFB1M-rs869120 with eGFR." (PMID 38858654, 2024).
Hyperglycemia (1 paper, 2022). An increased concentration of glucose in the blood. "We have reported that a variant of the gene encoding transcription factor B1 mitochondrial (TFB1M) is associated with reduced insulin secretion, hyperglycemia, and future risk of T2D." (PMID 35148993, 2022).
Kabuki syndrome (1 paper, 2024). Kabuki syndrome (KS) is a multiple congenital anomaly syndrome characterized by typical facial features, skeletal anomalies, mild to moderate intellectual disability and postnatal growth deficiency. "TFB1M is a mitochondrial transcription specificity factor that maintains homeostasis of oxidative phosphorylation and glycolysis, pathways that have been shown to be dysregulated in KMT2D-deficient lung cancers, epithelial cells, and Kabuki Syndrome patients." (PMID 39578878, 2024).
lung carcinoma (1 paper, 2024). "Notably, KMT2D-deficient lung cancer cells depend on proper glycolytic activities for survival, which is compatible with the notion that loss of TFB1M may be lethal for KMT2D-deficient cells." (PMID 39578878, 2024).
malignant astrocytoma (1 paper, 2016). "In malignant astrocytoma cells, decreased mtDNA copy numbers correlate with increased levels of mitochondrial POLG and mitochondrial transcription factors (TFAM, and TFB1M, and TFB2M)." (PMID 27486856, 2016).
schizophrenia (1 paper, 2016). A major psychotic disorder characterized by abnormalities in the perception or expression of reality. "To address this issue we measured levels of mRNA for six potential reference genes (GAPDH, PPIA, SNCA, NOL9, TFB1M and SKP1) in three cortical regions (Brodmann’s areas (BA) 8, 9 and 44) from 30 subjects with schizophrenia and 30 age and sex matched controls." (PMID 27206773, 2016).
tumour (2 papers, 2018 to 2024). "Moreover, the key mtDNA transcription factors POLRMT, TFAM, TFB1M and TFB2M were down-regulated in the GBM50 and GBM3 tumours." (PMID 30208958, 2018).
TFB1M also shares sentences with these, for which no sentence is quoted: mitochondrial disease (2 papers); breast carcinoma (1); cancer (1); mastitis (1); muscular atrophy (1); ovarian carcinoma (1).